LSR (lipolysis stimulated lipoprotein receptor)
Diseases named in the same sentence as LSR in open-access papers (continued):
Sharing a sentence is not in itself a finding about the gene and the disease.
lung adenocarcinoma (4 papers, 2021 to 2024). A carcinoma that arises from the lung and is characterized by the presence of malignant glandular epithelial cells. "In human lung adenocarcinoma cells, downregulation of the tricellular tight junction molecule angulin-1/LSR causes malignancy via EGF-dependent CLDN-2 and TGF-dependent cellular metabolism." (PMID 38001653, 2023). "We investigated how loss of angulin-1/LSR affects the malignancy of lung adenocarcinoma cell line A549 and normal human lung epithelial (HLE) cells." (PMID 36961882, 2023). "The use of both AG1478 and EW-7197 may provide a clinical therapeutic approach for lung adenocarcinoma caused by loss of angulin-1/LSR." (PMID 36961882, 2023). "We previously reported that the class I and II HDAC inhibitors TSA and Quisinostat (JNJ) have potential for use in therapy for lung adenocarcinoma via changes in the expression of angulin-1/LSR and CLDN-2." (PMID 38338691, 2024). "The loss of angulin-1/LSR promotes the malignancy via EGF-dependent CLDN-2 and TGF-β-dependent cell metabolism in human lung adenocarcinoma." (PMID 38338691, 2024). "The downregulation of angulin-1/LSR induces the malignancy of lung adenocarcinoma via EGF-dependent CLDN-2 and TGF-β-dependent cell metabolism." (PMID 38338691, 2024). "TSA and Quisinostat have the potential to be used in the treatment of lung adenocarcinoma by altering the expression of angulin-1/LSR and CLDN-2." (PMID 38001653, 2023). "In the lung adenocarcinoma tissues examined in the present study, expression of claudin-2 was higher than in normal lung tissues, while angulin-1/LSR was poorly or faintly expressed." (PMID 36961882, 2023). "To investigate how knockdown of LSR induced malignancy, cell proliferation and migration in lung adenocarcinoma, we first performed DNA microarray analysis in lung adenocarcinoma A549 cells transfected with the siRNAs of LSR." (PMID 36961882, 2023). "In the present study, we investigated the role and regulation of tTJ protein angulin-1/LSR in the malignancy of human lung adenocarcinoma compared to normal lung epithelial cells." (PMID 36961882, 2023). "To investigate whether knockdown of LSR affected cell proliferation, cell migration and the cell metabolism in lung adenocarcinoma, we performed knockdown of LSR using the siRNA of LSR and examined the cell cycle, cell migration and cell metabolism." (PMID 36961882, 2023). "Furthermore, downregulation of angulin-1/LSR induces malignancy via EGF-dependent CLDN-2 in a human lung adenocarcinoma cells." (PMID 34944960, 2021). "The downregulation of angulin-1/LSR induces malignancy via the upregulation of EGF-dependent CLDN-2 and cell metabolism via TGF-β signaling that induces EMT in lung adenocarcinoma." (PMID 38338691, 2024). "In conclusion, downregulation of angulin-1/LSR induces malignancy via EGF-dependent claudin-2 and TGF-β-dependent cell metabolism in human lung adenocarcinoma." (PMID 36961882, 2023). "In the present study, we found that downregulation of angulin-1/LSR induced malignancy via upregulation of EGF-dependent CLDN-2 and TGF-β-dependent cell metabolism in human lung adenocarcinoma." (PMID 36961882, 2023). "The HDAC inibitors trichostatin A (TSA) and Quisinostat (JNJ-2648158) increase angulin-1/LSR, decrease CLDN-2, promote G1 arrest and prevented the migration of lung adenocarcinoma A549 cells." (PMID 34944960, 2021).
lung carcinoma (4 papers, 2021 to 2024). "CLDN-2, upregulated in lung cancer tissues, results in the proliferation of lung cancer cells, while the downregulation of angulin-1/LSR causes malignancy." (PMID 36297347, 2022). "In in vitro functional experiment, we found that the proliferation ability of lung cancer cells was suppressed significantly after LSR downregulation." (PMID 33763152, 2021). "In summary, LSR was located on Ch.9q and was found to be an oncogene that is increased in lung cancer." (PMID 33763152, 2021). "Through bioinformatics analysis, it was found that LSR plays an important role in the progression of lung cancer." (PMID 33763152, 2021). "In this study, we evaluated the clinicopathological and oncogenic character of LSR in lung cancer and found that LSR mRNA and protein levels were upregulated in NSCLC and correlated to an advanced stage and shorter survival time of NSCLC." (PMID 33763152, 2021). "After transfection of si-LSR into lung cancer cell lines, LSR expression in A549 and H1299 cells was significantly decreased." (PMID 33763152, 2021). "Here, the candidate oncogene LSR on Ch.9q was obtained and assessed by bioinformatics analysis of The Cancer Genome Atlas (TCGA) dataset of lung cancer." (PMID 33763152, 2021). "Besides, the metastasis ability of lung cancer cells was also significantly suppressed after the LSR knockdown." (PMID 33763152, 2021). "Furthermore, we verified that LSR promoted cell proliferation, migration, and invasion by upregulating its expression in lung cancer." (PMID 33763152, 2021). "Through the bioinformatics analysis of TCGA dataset, we found that LSR might be a potential oncogene of lung cancer." (PMID 33763152, 2021). "In summary, LSR may be involved in mediating the occurrence and development of lung cancer by regulating the FoxO signaling pathway and the ErbB signaling pathway." (PMID 33763152, 2021). "Using in vitro analysis, our data revealed that LSR could promote lung cancer progression by regulating cell proliferation, migration, and invasion." (PMID 33763152, 2021). "LSR may also activate the SARS−CoV−2 S proteins and increase the viral infection of lung cancer cells, along with host co-receptors that might be involved in cell infection, such as NETO2, GRP87, and transmembrane protease serine 4 (TMPRSS4)." (PMID 39228892, 2024).
endometriosis (3 papers, 2016 to 2021). The growth of functional endometrial tissue in anatomic sites outside the uterine body. "Loss of angulin-1/LSR promotes the progression of endometriosis and EEC via multiple signaling pathways, Hippo/YAP, JNK, AMPK and HDAC, and CLDNs." (PMID 34944960, 2021). "In EEC tissues, angulin-1/LSR and ASPP2 are reduced and CLDN-2 is overexpressed together with malignancy, while in endometriosis tissues a change in the localization of angulin-1/LSR and CLDN-2 is observed." (PMID 34944960, 2021). "In EEC tissues, angulin-1/LSR and ASPP2 are reduced and claudin-2 is overexpressed during malignancy, while in the tissues of endometriosis changes in localization of angulin-1/LSR and claudin-2 are seen." (PMID 34944960, 2021). "This review highlights how downregulation of angulin-1/LSR promotes development of endometriosis and EEC and discusses about the roles of angulin-1/LSR and its related proteins, including claudins and ASPP2." (PMID 34944960, 2021). "This review highlights how the loss of angulin-1/LSR promotes the progression of endometriosis and EEC and discusses the possibility of therapeutic targeting for angulin-1/LSR via multiple signaling pathways and its related proteins." (PMID 34944960, 2021). "In endometriosis and endometrioid-endometrial carcinoma (EEC), angulin-1/LSR is localized not only in the subapical region, but also throughout the lateral region, and angulin-1/LSR in the cancer is reduced during the malignancy." (PMID 34944960, 2021). "In endometriosis and G1 and G2 of EEC, ASPP2 expresses as well as PAR3 and angulin-1/LSR in the subapical region, whereas ASPP2 decreases in G3 of EEC." (PMID 34944960, 2021). "It is possible that angulin-1/LSR may have multiple functions in normal, endometriosis and EEC tissues." (PMID 34944960, 2021). "Accordingly, angulin-1/LSR, ASPP2 and CLDN-2 may be as biomarkers for diagnosis or targets for treatment of endometriosis and EEC." (PMID 34944960, 2021).
gastric cancer (3 papers, 2018 to 2025). A primary or metastatic malignant neoplasm involving the stomach. "In pilot study, we confirmed the expression of LSR in some gastric cancer specimen, however, the function of LSR expression in GC has been obscure." (PMID 30250639, 2018). "Live-cell confocal microscopy demonstrated that anti-LSR mAb reduced lipid uptake (green fluorescence) in MDA-MB-231 cells, consistent with literature reports that LSR promotes lipid uptake and fatty acid oxidation in gastric cancer." (PMID 41040511, 2025).
Obesity (3 papers, 2014 to 2022). Accumulation of substantial excess body fat. "The differences in the function and role of LSR as a lipoprotein receptor and the involvement of LSR in obesity-dependent epithelial barrier attenuation should be clarified in future studies." (PMID 31330820, 2019). "Originally, LSR was identified as a membrane protein involved in the uptake and clearance of triglyceride-rich lipoproteins in the liver; however, to the best of our knowledge, its association with human obesity and hyperlipidemia has not been demonstrated yet." (PMID 35729527, 2022).
pancreatic cancer (3 papers, 2020 to 2023). "In pancreatic cancer, angulin-1/LSR contributes to the epithelial barrier and malignancy via the growth factors EGF and TGF-β." (PMID 36961882, 2023). "EW-7197 prevents changes of the distribution and barrier function of angulin-1/LSR by TGF-β1 in pancreatic cancer." (PMID 36961882, 2023). "In pancreatic cancer, angulin-1/LSR also contributes to the epithelial barrier and malignancy via the growth factors EGF and TGF-β." (PMID 36961882, 2023). "It prevents ulcerative colitis-associated fibrosis and inflammation as well as changes in the distribution of angulin-1/LSR and the epithelial barrier function caused by TGF-β in a pancreatic cancer cell line." (PMID 33182652, 2020).
viral infection (3 papers, 2024 to 2025). "Under either condition, knockdown of LSR led to a significant increase in viral infection, as evidenced by increased luciferase activity, GFP intensity, VSV phosphoprotein (VSV-P) copy numbers, and Spike copy numbers (Fig. EV2F)." (PMID 39443717, 2024). "We also explored the role of LSR on viral infection when the SARS-CoV-2 was bound to cell receptors." (PMID 39443717, 2024). "The results showed that knockdown of LSR significantly enhanced virus infection and Spike protein-mediated syncytium formation, while overexpression of LSR resulted in a significant decrease in syncytia formation following VSV-SARS-CoV-2 infection in both the Caco-2 and hACE2-HIEC-6 cells." (PMID 39443717, 2024). "Further, we used pseudovirus assays to determine whether LSR regulates viral infection at the level of entry." (PMID 39443717, 2024). "Loss of endogenous LSR enhances ACE2-dependent infection by SARS-CoV-2 Spike (S) protein-pseudotyped virus and authentic SARS-CoV-2 virus, and exogenous administration of LSR protects against viral infection." (PMID 39443717, 2024). "Exogenous administration of LSR protects against viral infection." (PMID 39443717, 2024). "NETO2 and lipolysis-stimulated lipoprotein receptor (LSR) may also activate SARS-CoV-2 S proteins and increase the viral infection of LC cells, while LSR is related to Clostridium difficile cell binding, to regulate cell proliferation, invasion, and migration via MAPK signaling." (PMID 41440381, 2025).
Alzheimer disease (2 papers, 2022). A progressive, neurodegenerative disease characterized by loss of function and death of nerve cells in several areas of the brain leading to loss of cognitive function such as memory and language. "Since LSR expression is higher in astroglia as compared to neurons, we sought to determine if astroglial LSR deficiency could lead to cognitive defects similar to those of Alzheimer’s disease (AD)." (PMID 35216163, 2022). "We recently reported that glia-specific suppression of the lipolysis-stimulated lipoprotein receptor (LSR) gene leads to Alzheimer’s disease-like memory deficits." (PMID 35955777, 2022).
deafness (2 papers, 2015 to 2025). An inherited or acquired condition characterized by the complete loss of the ability to hear from one or both ears. "In this sense, the p.P69H mutant protein was the first and only variant that showed both weakened localization at TCs of angulin-1/LSR knockdown cells and a milder auditory phenotype ‘partial deafness’." (PMID 25668204, 2015).
-CoV-2 infection (1 paper, 2024). "In accordance with VSV-SARS-CoV-2 infection data (Fig. EV2O), LSR overexpression reduced the levels of infection down to 11%, whereas silencing LSR led to a 10.8-fold increase in SARS-CoV-2 infection by analyzing the viral RNA through RT-qPCR." (PMID 39443717, 2024).
acute pancreatitis (1 paper, 2022). An acute inflammatory process that leads to necrosis of the pancreatic parenchyma. "We investigated the effects of lipolysis-stimulated lipoprotein receptor (LSR) on the tight junctions (TJs) of pancreatic ductal epithelial cells (PDECs) in hypertriglyceridemic acute pancreatitis (HTGAP)." (PMID 35463981, 2022). "Among the TJ proteins, LSR protein expression was significantly lower in the HTGAP group than in the acute pancreatitis (AP) group." (PMID 35463981, 2022).
bladder tumors (1 paper, 2008). "From the data generated in a previous microarray screening of bladder tumors we identified LSR as an interesting candidate gene for further analysis." (PMID 18647386, 2008).
chronic sinusitis (1 paper, 2021). "To investigate the roles of angulin-1/LSR in the epithelial barrier of human nasal epithelia, we used primary cultured human nasal epithelial cells (HNECs) isolated from nasal mucosal tissues of patient with hypertrophic rhinitis or chronic sinusitis who underwent inferior turbinectomy." (PMID 34445093, 2021).
colorectal adenocarcinoma (1 paper, 2017). The most common type of colorectal carcinoma. "Here we generated with the same approach an LSR knockout in the human colorectal adenocarcinoma cell line CaCo-2." (PMID 27391068, 2017). "However, since the human colorectal adenocarcinoma cell line CaCo-2 is an important cancer cell model, we aimed to disrupt the LSR gene also in CaCo-2 cells via CRISPR/Cas9." (PMID 27391068, 2017).
endometrioid-endometrial carcinoma (1 paper, 2021). "Downregulation of angulin-1/LSR correlates with the malignancy in various cancers, including endometrioid-endometrial carcinoma (EEC)." (PMID 34944960, 2021).
epilepsy (1 paper, 2025). A brain disorder characterized by episodes of abnormally increased neuronal discharge resulting in transient episodes of sensory or motor neurological dysfunction, or psychic dysfunction. "While LSR’s role in neuroinflammation, PARP1’s involvement in neuronal survival, and ZNF619’s regulation of transcription are consistent with epilepsy pathophysiology, these associations are based on a limited sample size and bulk‐tissue expression." (PMID 40624693, 2025).
epithelial ovarian cancer (1 paper, 2025). "High expression of the LSR (lipolysis-stimulated lipoprotein receptor) gene in epithelial ovarian cancer (EOC) is associated with a poorer prognosis for patients." (PMID 41465326, 2025).
familial intrahepatic cholestasis (1 paper, 2025). An instance of intrahepatic cholestasis that is caused by an inherited modification of the individual's genome. "Patients with an unclear progressive familial intrahepatic cholestasis (PFIC)-like clinical picture should therefore undergo genetic testing of the LSR gene." (PMID 40980121, 2025).
hearing loss (1 paper, 2017). "Collectively, these findings suggest that both tTJ proteins TRIC and LSR have crucial roles for the differentiated cochlear cell survival, and that HDAC inhibitors may be potential therapeutic agents to prevent hearing loss." (PMID 28767685, 2017).
hyperlipidemia (1 paper, 2022). "The anti-LSR mAb inhibited tumor growth in vivo without causing hyperlipidemia and impeded cell proliferation promoted by VLDL in vitro." (PMID 35729527, 2022).
hypertriglyceridemia (1 paper, 2022). A laboratory test result indicating elevated triglyceride concentration in the blood. "LSR (lipolysis stimulated lipoprotein receptor) is involved in the clearance of triglyceride-rich lipoprotein, and knockdown of LSR promoted hypertriglyceridemia and increased serum levels of apolipoprotein (Apo)B and E, which are associated with LDL and chylomicrons." (PMID 36234935, 2022).
IgG4-related disease (1 paper, 2022). "To examine the roles of p63, CGN and angulin-1/LSR in normal human salivary gland duct epithelial cells, we used HSDE cells derived from salivary gland tissues of patients with IgG4-related disease that were previously reported." (PMID 35681564, 2022).
intrahepatic cholestasis (1 paper, 2025). A cholestasis characterized by impairment of the bile flow caused by obstruction located in the liver. "We report on three children with novel variants in the lipolysis-stimulated lipoprotein receptor (LSR) gene with clinical presentation with early onset intrahepatic cholestasis and the main symptom being uncontrollable itching." (PMID 40980121, 2025). "We report on three children with early onset intrahepatic cholestasis caused by novel variants in the LSR gene." (PMID 40980121, 2025).
metachromatic leukodystrophy (1 paper, 2020). A rare lysosomal storage disorder characterized by intralysosomal accumulation of sulfatides in various tissues, leading to progressive deterioration of motor and neurocognitive function. "In our data, in addition to APOE, we found that the lipoprotein receptor LSR and the lysosomal enzyme ARSA—a gene in which homozygous mutations cause metachromatic leukodystrophy —were elevated in HAM." (PMID 32610143, 2020).
metastatic tumors (1 paper, 2018). "LSR was overexpressed in most of primary GC and metastatic tumors, but not in normal tissues." (PMID 30250639, 2018).
nonsyndromic deafness (1 paper, 2017). An auditory system disease that is associated with permanent hearing loss caused by damage to structures in the inner ear and/or the middle ear, which is not associated with other signs and symptoms. "Consistently, LSR has two homologous genes known as ILDR1 and ILDR2, of which mutations in ILDR1 result in familial nonsyndromic deafness." (PMID 28767685, 2017).
ovarian epithelial tumor (1 paper, 2021). A benign, borderline, or malignant tumor that originates from the surface epithelium of the ovary. "The angulin-1/LSR antibody can inhibit ovarian epithelial tumor growth." (PMID 34944960, 2021).
papillary adenocarcinoma (1 paper, 2023). A morphologic variant of adenocarcinoma. "In the present study Immunohistochemistry showed that CLDN-2 expression in all papillary and invasive lung adenocarcinoma tissues was higher than in normal lung tissues, whereas angulin-1/LSR was highly expressed only in one papillary adenocarcinoma and faintly expressed in the other cases." (PMID 36961882, 2023).
prostate carcinoma (1 paper, 2017). A carcinoma that arises from epithelial cells of the prostate gland. "We confirmed our discovery of unknown EMT genes in prostate cancer by testing expression of LSR, S100A14, and DPYSL3 in a PC3 prostate cancer cell line model of EMT." (PMID 28651527, 2017). "We found three groups of genes in the EMT differentially expressed list: a) known EMT genes (e.g. CDH1, ZEB1, TGFB, CDH2, VIM, TIMP1), b) EMT genes previously unknown in prostate cancer (LSR, S100A14, DPYSL3) and c) novel EMT genes (including C1orf116)." (PMID 28651527, 2017). "In addition, we also identified EMT genes that had only been described in a sub-set of malignant disease states, but were previously unknown in prostate cancer (e.g. LSR, S11A14, DPYSL3), implying a common EMT program across multiple cancer types." (PMID 28651527, 2017).
Stroke (1 paper, 2021). Sudden impairment of blood flow to a part of the brain due to occlusion or rupture of an artery to the brain. "In accordance with observations in mouse models of stroke and MS, we found that decreased expression of tricellulin and LSR/angulin-1 in IL-1βhi-stimulated pMBMECs was accompanied with a trend for increased permeability of pMBMEC monolayers to small molecules." (PMID 33912914, 2021).